SLC25A36 (solute carrier family 25 member 36)
Description:
Mitochondrial transporter that imports/exports pyrimidine nucleotides into and from mitochondria. Selectively transports cytosine, guanosine, inosine and uridine (deoxy)nucleoside mono-, di-, and triphosphates by antiport mechanism. Catalyzes uniport at much lower rate. May import (deoxy)nucleoside triphosphates in exchange for intramitochondrial (deoxy)nucleoside mono- and diphosphates, thus providing precursors necessary for de novo synthesis of mitochondrial DNA and RNA while exporting products of their catabolism. Participates in mitochondrial genome maintenance, regulation of mitochondrial membrane potential and mitochondrial respiration.
Synonyms: FLJ10618; PNC2; HHF8
Tractability: Antibody: UniProt predicts a signal peptide or a membrane-spanning region. PROTAC: ubiquitination databases record sites on it; its protein half-life has been measured.
Gene: Protein-coding gene on chromosome 3 (140,941,801 to 140,980,995, forward strand). Ensembl gene ENSG00000114120.
Subcellular location: Mitochondrion inner membrane
Subcellular location (Human Protein Atlas): Cytosol; Mitochondria; Nucleoplasm
Gene Ontology:
Molecular function: pyrimidine nucleotide transmembrane transporter activity
Biological process: pyrimidine nucleotide import into mitochondrion; nucleotide transport; transmembrane transport
Cellular component: mitochondrion; mitochondrial inner membrane
Genetic constraint (gnomAD): Loss-of-function variants: 10 observed, 18.45 expected, observed/expected ratio (o/e) 0.54, 90% interval 0.33 to 0.92. The upper end of that interval is the gene's LOEUF score, 0.92, which puts it in group 3 of 6, group 1 being the genes least tolerant of losing a copy. Missense variants: 201 observed, 269.61 expected, observed/expected ratio (o/e) 0.75, 90% interval 0.66 to 0.84. Synonymous variants: 101 observed, 98.1 expected, observed/expected ratio (o/e) 1.03, 90% interval 0.88 to 1.22.
Homologues: Orthologues: chimpanzee SLC25A36 (99% identical), macaque SLC25A36 (98% identical), dog SLC25A36 (97% identical), pig SLC25A36 (97% identical), mouse Slc25a36 (96% identical), guinea pig SLC25A36 (94% identical), rat Slc25a36l1 (93% identical), zebrafish slc25a36a (87% identical), tropical clawed frog slc25a36 (86% identical). Paralogues in human: SLC25A33 (60% identical), SLC25A31 (26% identical), SLC25A32 (26% identical), SLC25A5 (25% identical), SLC25A13 (24% identical), SLC25A4 (24% identical), SLC25A6 (24% identical), SLC25A23 (24% identical), SLC25A12 (23% identical), SLC25A28 (23% identical), SLC25A24 (23% identical), SLC25A37 (23% identical), and 37 more.
Diseases named in the same sentence as SLC25A36 in open-access papers:
SLC25A36 is named in the same sentence as 11 diseases in open-access papers, as found by Europe PMC text mining. Sharing a sentence is not in itself a finding about the gene and the disease. The quoted sentences say what the papers report.
cardiac hypertrophy (1 paper, 2020). "Interestingly, Slc35e3 was found to be up-regulated during cardiac hypertrophy, while Slc25a36 has been previously identified to be involved in the metabolism of nucleic acids in cardiac cells." (PMID 33102519, 2020).
cervical cancer (1 paper, 2014). A primary or metastatic malignant neoplasm involving the cervix. "Application to an integrative oncogenomics study, involving HPV-transformed cell lines, confirmed genes CADM1 and SLC25A36, known to be implicated in the development of cervical cancer." (PMID 25278371, 2014).
developmental delay (1 paper, 2021). "We report the first known case of SLC25A36 deficiency in a 12-year-old patient with hypothyroidism, hyperinsulinism, hyperammonemia, chronical obstipation, short stature, along with language and general developmental delay." (PMID 34576089, 2021). "Consistent with the patient’s general developmental delay, SLC25A36 is highly expressed in the cerebral cortex and furthermore in the brainstem and pineal gland." (PMID 34576089, 2021).
Hyperammonemia (1 paper, 2021). An increased concentration of ammonia in the blood. "SLC25A36 is supposedly not expressed in the liver, but nevertheless, our patient presented with hyperammonemia." (PMID 34576089, 2021).
metastatic prostate carcinoma (1 paper, 2015). A carcinoma that arises from the prostate gland and has spread to other anatomic sites. "Four genes in particular, MALAT1, CLCN5, MLL3, and SLC25A36, that were up-regulated in metastatic prostate cancer compared to primary prostate cancer were also displayed an enhanced expression in PC3-WT osteoblast co-cultures and PC3-SostKO osteoblast co-cultures compared to PC3 alone." (PMID 27600237, 2015).
cancer (1 paper, 2014). A tumor composed of atypical neoplastic, often pleomorphic cells that invade other tissues. "Overexpression of several of these genes has been previously identified in various cancer types: Slc25a36 (cervical) and Znf146 (colorectal and pancreas)." (PMID 25474466, 2014).
SLC25A36 also shares sentences with these, for which no sentence is quoted: age (1 paper); hyperinsulinism (1); hypothyroidism (1); prostate carcinoma (1); tumor (1).